CCBE1 (collagen and calcium binding EGF domains 1)
Diseases named in the same sentence as CCBE1 in open-access papers (continued):
Sharing a sentence is not in itself a finding about the gene and the disease.
tumor (continued). "Next, we explored the prognostic value of tumor stromal expression of CCBE1 in our cohort of CRC samples." (PMID 32089745, 2020). "Statistically, CCBE1 expression in both tumor stroma and tumor cells was positively correlated with lymphatic vessel density." (PMID 32089745, 2020). "Next, to further explore the role of CCBE1 in tumor lymphangiogenesis, tube formation and wound healing assays were performed with HLECs." (PMID 32089745, 2020). "Our results indicated that tumor stromal expression of CCBE1 is associated with poor prognosis in CRC and that high CCBE1 expression in both epithelial CRC cells and tumor stroma is a more accurate poor prognostic marker for CRC." (PMID 32089745, 2020). "Meanwhile, CCBE1-overexpressing tumors displayed a higher number of human mitochondrion protein-positive tumor cells in sentinel LNs (popliteal LN) and all three draining nodes than control tumors." (PMID 32089745, 2020). "Our studies demonstrate that CCBE1 protein is expressed in tumor cells and stroma but hardly in normal colonic epithelial cells, which indicates that CCBE1 is overexpressed in CRC cells." (PMID 32089745, 2020). "CCBE1 was expressed in not only CRC cells but also the tumor stroma; CCBE1 expression in each location was correlated with poor prognosis and lymph node (LN) metastasis." (PMID 32089745, 2020). "In human GISTs, we found that CCBE1 was specifically located in the vessel wall of the tumor tissues." (PMID 27506146, 2016). "CCBE1 has been shown to act as both a tumour suppressor and as an oncogenic factor." (PMID 36672761, 2022). "Thus, high CCBE1 expression in both epithelial cells and tumor stroma is a more accurate prognostic marker for CRC." (PMID 32089745, 2020). "Moreover, univariate and multivariate analyses showed that CCBE1 expression in tumor cells, tumor stroma or both tumor cells and stroma was an independent prognostic factor in CRC." (PMID 32089745, 2020). "Moreover, CCBE1 expression in the tumor environment and its clinicopathological implication in CRC remain undescribed." (PMID 32089745, 2020). "In addition, our study further showed that high CCBE1 expression in tumor stroma is an independent poor prognostic marker for DFS and OS in CRC." (PMID 32089745, 2020). "Taken together, these data indicated that CCBE1 in the tumor stroma might contribute to CRC lymphangiogenesis and progression." (PMID 32089745, 2020). "The downregulation of CCBE1 mRNA in CRC tissues could be due to the mixture of cell types within a tumor, particularly the presence of some CAFs with decreased CCBE1 mRNA levels." (PMID 32089745, 2020). "Notably, CCBE1 expression was significantly higher in tumor margins than in adjacent normal tissues." (PMID 32089745, 2020). "Then the Chi-square test was used to assess the correlations between CCBE1 expression and clinicopathologic parameters (including age, gender, NIH risk degree, tumor size, tumor site, mitotic figures, tumor bleeding, Ki67 classification, recurrence, and NIH invasion)." (PMID 27506146, 2016). "However, considering CCBE1 as a secreted protein and the complexity of tumor microenvironment, additional studies need to be performed to figure out the underlying mechanism of how CCBE1 affects GIST response to imatinib." (PMID 27506146, 2016). "Taken together, we concluded that CCBE1 could partially counteract the anti-tumor effects of imatinib in GIST-T1 cells." (PMID 27506146, 2016). "The results demonstrated that the expression level of CCBE1 in GIST tissues was closely correlated with NIH risk degree (p < 0.001), tumor size (p < 0.001), tumor site (p = 0.012), mitotic figures (p = 0.008), Ki67 classification (p = 0.005), recurrence (p = 0.001) and invasion (p < 0.001)." (PMID 27506146, 2016).
tumor (continued). "These transcripts represent mRNAs that are expressed from 4-cell EGA though the preimplantation period and include CCBE1, a tumour suppressor gene with a suggested role in extracellular matrix remodelling and the cyclic AMP antagonist PDE6B responsible for removing cAMP." (PMID 23717564, 2013). "If CCBE1 activity is modulated by hydroxylation of Asp/Asn residues by BAH, it could be predicted that silencing of CCBE1 may result in a similar tumour-promoting effect to that of BAH loss, although this remains to be determined." (PMID 19935792, 2010). "Interestingly, although CCBE1 was not differentially expressed between normal and tumor stroma tissues, high CCBE1 protein expression in tumor stroma was associated with shorter overall survival (OS) and disease-free survival (DFS) in CRC." (PMID 32089745, 2020). "Thus, besides activating VEGFC processing, overexpression of CCBE1 in CRC could also enhance the release of VEGFC to promote tumor lymphangiogenesis." (PMID 32089745, 2020). "Thus, expression of CCBE1 is also inversely correlated with tumour cell survival." (PMID 19935792, 2010). "CCBE1 has been reported to be downregulated in HCC, preventing tumor progression by promoting mitochondrial fusion." (PMID 40026364, 2025). "In contrast with the human samples, ADARB1 and CCBE1 were upregulated and COL11A1 and MUC16 were downregulated in FGF14 overexpressing xenograft tumors, which emphasized the tumor suppressing role of FGF14 in NSCLC." (PMID 32707902, 2020). "Our study elucidates the lymphangiogenic role of CCBE1 in CRC progression and reveals the mechanism by which TGF-β suppresses tumor lymphangiogenesis." (PMID 32089745, 2020). "Recently, CCBE1 was found to be oncogenic, conferring resistance to imatinib in GSIT by enhancing tumor angiogenesis." (PMID 32089745, 2020). "In this study, we clearly show that overexpression of CCBE1 in CRC cells promotes VEGFC proteolysis and activation and that CCBE1 enhances tumor lymphangiogenesis and lymphatic metastasis in CRC." (PMID 32089745, 2020). "In the study of CCBE1 expression in 325 patient tissues, we found that the CCBE1 expression was positively related with NIH classification, tumor size and the number of mitotic figures." (PMID 27506146, 2016). "Univariate Cox proportional hazards regression analysis indicated that CCBE1 expression, modified NIH criteria, tumor size, mitoses, NIH invasion, recurrence and Ki67 classification were hazardous prognostic factors for the overall survival of GIST patients." (PMID 27506146, 2016). "Expression levels of FCN3 and CCBE1 were found to be significantly reduced in tumor tissues compared to their non-tumor matched normal counterparts from the GTEx database (Figure 2Gb and Hb)." (PMID 40026364, 2025). "Therefore, our study found that during PCa pathogenesis, the disorganized expression of CRISP3, OGN, SPOCK3, COL4A6, CCBE1, and FLRT3 leads to ECM dysfunction and promotes angiogenesis and tumor development." (PMID 37251946, 2023). "Indeed, both cancer- and CAF-secreted CCBE1 mediates activation of VEGF-C within ECM and induce lymphangiogenesis and tumor progression." (PMID 36906534, 2023). "The mRNA expression of CCBE1 and ADARB1 was significantly upregulated, while the expression of COL11A1 and MUC16 was significantly downregulated in LUAC samples compared with non-tumor samples." (PMID 32707902, 2020). "High-risk prognostic genes BMP4, CELSR3, GPRC5C, and RUNDC3B, highly expressed in Epithelial Cells, CCBE1 showed expression in Leydig cells, SCGB2A2 highly expressed in Epithelial Cells and Cancer cells, suggesting that Epithelial cell play an important role in tumor growth and initiation." (PMID 37985782, 2023). "However, the role of CCBE1 in tumor lymphangiogenesis during CRC progression has not been defined in vitro and in vivo, and the mechanism underlying dysregulated CCBE1 expression in CRC remains obscure." (PMID 32089745, 2020).
tumor (continued). "Interestingly, we noticed that CCBE1 was modestly expressed in both normal and tumor stroma, with no significant differential expression between these two tissues." (PMID 32089745, 2020). "In addition, in the subgroups of patients whose tumor size ≥5 cm, mitoses II and III, Ki67 classification II and III or in NIH invasion III, IV and V, the DFS of CCBE1 low expression group was also superior to that of CCBE1 high expression group." (PMID 27506146, 2016). "Furthermore, we have shown that rCCBE1 protein can facilitate the potential of angiogenesis and partially reduce the anti-tumor effects of imatinib to GIST cells, suggesting that CCBE1 might be used as a potential clinical therapy target for GIST." (PMID 27506146, 2016). "Thus, it would be of great interest to investigate whether E2F7/8 not only control CCBE1 and FLT4 during developmental lymphangiogenesis but also during tumor dissemination." (PMID 24069224, 2013). "Furthermore, we confirmed that CCBE1 was co-localized with CD31 (a marker of vascular endothelial cells), but not with LYVE-1 (lymphatic vessel endothelial hyaluronan receptor 1, a marker of lymphatic endothelial cells), by IHC in serial sections of GIST tumor tissues." (PMID 27506146, 2016).
cancer (16 papers, 2010 to 2024). A tumor composed of atypical neoplastic, often pleomorphic cells that invade other tissues. "This study demonstrated that TGF-β suppresses the expression and lymphangiogenic function of CCBE1 in cancer-associated fibroblasts and CRC cells." (PMID 35222551, 2022). "Among them, only six genes—MMP11, ANGPTL1, GSTM5, IQGAP3, UHRF1, and CCBE1—were shared across all analyzed carcinomas." (PMID 39596491, 2024). "None of the six genes (MMP11, ANGPTL1, GSTM5, IQGAP3, UHRF1, and CCBE1) have previously been categorized as carcinoma biomarkers collectively." (PMID 39596491, 2024). "While only a few studies have addressed this point in the context of lymphangiogenesis and cancer, to date, nothing is known about the mechanisms that transcriptionally regulate CCBE1 in the heart." (PMID 35222551, 2022). "As per previous studies, CCBE1 is indispensable for the development of lymphatic vessels which have important roles in lymphangiogenesis and cancer metastasis." (PMID 32934959, 2020). "VEGFC proteolytic processing and HLEC tube formation were inhibited by TGF-β and partially rescued by CCBE1 overexpression in SW837 cells and cancer-associated fibroblasts (CAFs)." (PMID 32089745, 2020). "Accumulating research has demonstrated that CCBE1 is vital in cancer biology." (PMID 35674190, 2022). "Currently, the relationship of CCBE1 with different types of cancer has been studied." (PMID 34440261, 2021). "Intriguingly, studies reporting the roles of CCBE1 in cancer are contradictory." (PMID 32089745, 2020). "As an initial investigation to identify a putative functional role for CCBE1, we, therefore, investigated whether CCBE1 has a function in cancer cell migration." (PMID 19935792, 2010). "As T-47D cells readily form colonies when sparsely seeded on plastic, we additionally examined whether expression of CCBE1 in T-47DmEcoR cells had a suppressive effect on the colony-forming ability of cancer cells." (PMID 19935792, 2010). "Further experiments detailing its cellular location, expression and function in normal and cancer cells will provide further insight into the function of CCBE1 and how it might contribute to carcinogenesis." (PMID 19935792, 2010). "However, data indicate that CCBE1 may have particular effects depending on the type of cancer, which has generated some controversy about its role in cancer development." (PMID 34440261, 2021). "Similar to the downregulation of CCBE1 mRNA levels in these two types of cancer, TCGA CRC data showed significantly decreased CCBE1 mRNA expression in CRC." (PMID 32089745, 2020). "Moreover, re-expression of CCBE1 mRNA after treatment with combined 5-AZA and TSA suggests that deacetylation of histones also affects expression of CCBE1 in cancer." (PMID 19935792, 2010). "In the context of cancer, two studies performed in rectal cancer (RC) suggest that the gene related to the growth of tumor Stomatin-like protein 2 (SLP-2) might be regulating CCBE1 in the genesis of lymphatic tubes." (PMID 35222551, 2022). "As there is no anti-CCBE1 antibody suitable for immunohistochemistry, we examined CCBE1 expression in a small sample of primary carcinomas using ISH, which confirmed that CCBE1 mRNA was highly expressed in both NOSE and in normal ovarian stroma, as predicted by transcriptional profiling studies." (PMID 19935792, 2010).
cardiovascular disease (1 paper, 2026). "In parallel, single‐cell RNA sequencing (scRNA‐seq) was conducted in the same individuals to investigate differential expression of CCBE1, a recently implicated gene in cardiovascular disease, across PBMC populations." (PMID 41549547, 2026).
CCBE1 also shares sentences with these, for which no sentence is quoted: lymphangiectasia (4 papers); primary lymphedema (2); adenocarcinoma (1); Astrocytoma (1); Camptodactyly (1); choanal atresia (1); ciliopathies (1); cutaneous melanoma (1); glioblastoma (1); heart defects (1); Hennekam lymphangiectasia-lymphedema syndrome 2 (1); hereditary lymphedema III (1); Immunodeficiency (1); intestinal diseases (1); lymphatic disease (1); lymphedema-cholestasis syndrome (1); melanoma (1); rectal cancer (1); syndactyly (1); Urioste syndrome (1).